SIRT5 (sirtuin 5)
Diseases named in the same sentence as SIRT5 in open-access papers (continued):
Sharing a sentence is not in itself a finding about the gene and the disease.
chordoma (1 paper, 2024). Chordomas are rare malignant tumors arising from embryonic remnants of the notochord in axial skeleton. "This study was performed to investigate the regulatory effects of SIRT5 on cell proliferation, migration, and invasion and the underlying mechanism in chordoma." (PMID 38532359, 2024). "Given this background, this study aimed to explore the effects of SIRT5 on cell proliferation, migration, and invasion and the underlying mechanism in chordoma, which might provide a potential therapeutic intervention strategy for chordoma." (PMID 38532359, 2024). "Silencing of SIRT5 suppressed the cell proliferation, migration, and invasion of chordoma cells, while the results were reversed after c-myc overexpression." (PMID 38532359, 2024). "The effects of SIRT5 and c-myc on cell proliferation, migration, and invasion of chordoma cells were detected by cell counting kit-8, colony formation, and Transwell assays." (PMID 38532359, 2024). "Additionally, we used HEK-293T cells to further explore the mechanism by which SIRT5 affected the progression of chordoma." (PMID 38532359, 2024). "Besides, we found that silencing SIRT5 inhibited proliferation, migration, and invasion of chordoma cells, indicating that SIRT5 promoted malignant advancement of chordoma." (PMID 38532359, 2024). "Then, we conducted the in vitro study to explore the role of SIRT5 in chordoma." (PMID 38532359, 2024). "In this study, we found that SIRT5 was increased in chordoma tissues and cells." (PMID 38532359, 2024). "The results showed that SIRT5 expression was upregulated in chordoma tissues and cells." (PMID 38532359, 2024). "In summary, this finding indicated that SIRT5-mediated desuccinylation of c-myc promoted malignant advancement of chordoma, which might provide new ideas for the clinical treatment of chordoma." (PMID 38532359, 2024).
chronic heart failure (1 paper, 2019). "In addition to acute cardiac hypertrophy and cardiac dysfunction, SIRT5 KO was also found to induce chronic heart failure with aging, as early as 8 weeks of age, which is associated with reduced ATP production." (PMID 30759120, 2019).
congenital heart disease (1 paper, 2025). A heart disease that is present at birth. "Disruptions in the expression of Sirt5, Pfkm, and Lclat1 have been associated with mitochondrial dysfunction and also the onset of congenital heart disease, highlighting their importance in heart development." (PMID 41226629, 2025).
cutaneous melanoma (1 paper, 2019). A primary melanoma arising from atypical melanocytes in the skin. "Interestingly, SIRT5 is not necessary for BrafV600E-mediated cutaneous melanoma initiation and growth in vivo." (PMID 31456942, 2019).
Depression (1 paper, 2024). "Depression behaviors correlate with mitochondrial dysfunction and implicate SIRT5 in this pathophysiology, particularly in the citric acid cycle and oxidative phosphorylation pathways." (PMID 39404407, 2024).
disc degeneration (1 paper, 2023). "The team found that SIRT5 expression was reduced in IDD, which affected the activity of another protein and directly led to mitochondrial dysfunction and disc degeneration." (PMID 36653443, 2023). "The sirtuin 5 (SIRT5) protein helps maintain healthy mitochondria, a key factor in protecting against disc degeneration." (PMID 36653443, 2023). "Given the negative correlation between IDD and SIRT5 expression, we hypothesized that SIRT5 plays a protective role in compression-induced disc degeneration." (PMID 36653443, 2023).
endometrioid adenocarcinoma (1 paper, 2019). An adenocarcinoma characterized by the presence of malignant glandular epithelial cells resembling endometrial cells. "SIRT2 expression was lower in serous and endometrioid adenocarcinoma in Lu’s dataset, whereas SIRT5 was upregulated in those types of OC in Hendrix’s dataset compared with normal tissues." (PMID 31572453, 2019).
hearing loss (1 paper, 2024). "SIRT4, SIRT5, and SIRT6 lacked any evidence of involvement in hearing loss, but their expressions were slightly altered in an ARHL model of mice in various tissue types of an ARHL model of mice." (PMID 39204103, 2024).
Hyperglycemia (1 paper, 2019). An increased concentration of glucose in the blood. "None of these mice exhibited accelerated retinal dysfunction after induction of hyperglycemia, consistent with normal-appearing retinal morphology in hyperglycemic Sirt3−/− or Sirt5−/− mice." (PMID 30846716, 2019). "Mice lacking both SIRT3 and SIRT5 (Sirt3−/−Sirt5−/−) were equally susceptible to STZ-induced hyperglycemia compared to control littermates of various genotypes, including Sirt3+/−Sirt5+/−, Sirt3−/−Sirt5+/−, and Sirt3+/−Sirt5−/− mice." (PMID 30846716, 2019). "We found that mice lacking Sirt3 (Sirt3−/−) or Sirt5 (Sirt5−/−) were equally susceptible to STZ-induced hyperglycemia compared to wild-type controls." (PMID 30846716, 2019). "On the other hand, mice lacking both SIRT3 and SIRT5 exhibited significantly more inner retinal dysfunction following induction of hyperglycemia compared to hyperglycemic littermate controls." (PMID 30846716, 2019). "Because past studies have demonstrated that chronic systemic hyperglycemia induces mitochondrial damage, we first evaluated whether there is increased SIRT3 or SIRT5 protein expression in retinas from STZ-induced hyperglycemic, wild-type mice." (PMID 30846716, 2019). "However, mice lacking both SIRT3 and SIRT5 (Sirt3−/−Sirt5−/− mice) exhibited significant evidence of inner retinal dysfunction after induction of hyperglycemia compared to hyperglycemic littermate controls, although this dysfunction was not accompanied by gross morphological changes in the retina." (PMID 30846716, 2019). "As such, we induced hyperglycemia with streptozotocin in mice with monoallelic Nampt deletion from rod photoreceptors, mice lacking SIRT3, and mice lacking SIRT5 and tested multiple components of retinal function with electroretinography." (PMID 30846716, 2019).
Impaired glucose tolerance (1 paper, 2024). An abnormal resistance to glucose, i.e., a reduction in the ability to maintain glucose levels in the blood stream within normal limits following oral or intravenous administration of glucose. "Sirt5 KO mice exhibited more fat mass and impaired glucose tolerance." (PMID 39351529, 2024).
infarction (1 paper, 2021). A localised pathological necrosis of tissue resulting from obstruction of the blood supply usually by a thrombus, an embolus, or vascular torsion. "Compared with wild-type littermates, SIRT5 knockout exacerbates infarction, and this is reversed by pretreatment of malonate, implicating SIRT5 modulates protein succinylation in IR injury." (PMID 34957264, 2021).
influenza (1 paper, 2022). An acute viral infection of the respiratory tract, occurring in isolated cases, in epidemics, or in pandemics; it is caused by serologically different strains of viruses (influenzaviruses) designated A, B, and C, has a 3-day incubation period, and usually lasts for 3 to 10 days. "Knocking out SIRT5 enhances the replication of several DNA viruses, such as herpes simplex 1, human cytomegalovirus and adenovirus type 5, and the same study reported a potential increase in influenza replication, albeit non-significantly." (PMID 36095012, 2022).
injury (1 paper, 2023). Damage inflicted on the body as the direct or indirect result of an external force, with or without disruption of structural continuity. "The protective effects of SIRT1, SIRT3, and SIRT5 against cisplatin-induced kidney injury have been reported." (PMID 38034992, 2023).
ischemia reperfusion injury (1 paper, 2024). Adverse functional, metabolic, or structural changes in ischemic tissues resulting from the restoration of blood flow to the tissue (reperfusion), including swelling; hemorrhage; necrosis; and damage from free radicals. "Previous studies have demonstrated that quercetin, an active ingredient in BYHW, ameliorates myocardial cell apoptosis following ischemia-reperfusion injury via the DNA-PKcs-SIRT5 pathway." (PMID 39439466, 2024).
ischemic cardiomyopathy (1 paper, 2025). Ischemic cardiomyopathy is a cardiomyopathy in which a weakness in the muscle of the heart due to inadequate oxygen delivery to the myocardium with coronary artery disease being the most common cause. "Notably, patients with ischemic cardiomyopathy exhibit a 65 % decrease in SIRT5 protein expression; however, the observed hyposuccinylation was independent of SIRT5 activity." (PMID 41260100, 2025).
left ventricular hypertrophy (1 paper, 2019). Enlargement of the LEFT VENTRICLE of the heart. "Our earlier observation that Sirt5 deficiency enhances AMPK activation inspired us to assess the cardiac function in Sirt5 KO and WT mice after TAC, a well-characterized animal model for pressure overload-induced left ventricular hypertrophy." (PMID 30759120, 2019).
mastitis (1 paper, 2026). Inflammation of breast tissue during lactation or postpartum due to an obstructed duct or infection. "We found pronounced oxidative stress and cellular senescence in mammary tissues from cows with S. aureus mastitis, accompanied by marked downregulation of SIRT5." (PMID 41678546, 2026).
mesothelioma (1 paper, 2019). A usually malignant and aggressive neoplasm of the mesothelium which is often associated with exposure to asbestos. "SIRT3 and SIRT5 exhibited pro-survival effects in U2OS cells, whereas in mesothelioma cell lines SIRT3 and SIRT5 exerted pro-survival trends." (PMID 31608237, 2019). "In mesothelioma cell lines, SIRT3 and SIRT5 exerted pro-survival trends." (PMID 31608237, 2019). "Analysis of sirtuin family members crosstalk revealed that SIRT1 has negative effect on SIRT3 and SIRT5 protein levels in bone cells and this depends on the type of cellular stress, whereas positive effects were recorded in Mero-14 mesothelioma cells." (PMID 31608237, 2019).
multiple sclerosis (1 paper, 2014). A progressive autoimmune disorder affecting the central nervous system resulting in demyelination. "Genetic variability in HDAC9, along with variants in HDAC11, SIRT4 and SIRT5, has also been shown to influence brain volume in multiple sclerosis (MS) patients, as assessed used neuroimaging methods." (PMID 25322459, 2014). "As with the SIRT4 and SIRT5 genes, variants in HDAC11 were also shown to influence multiple sclerosis in terms of brain volume." (PMID 25322459, 2014).
neuropathy (1 paper, 2024). A disorder affecting the nervous system that manifests with pain, tingling, numbness, and/or muscle weakness. "Given our observation of mitochondrial alterations in PDN rats and the lack of correlation between SIRT4 and SIRT5 with DRG or neuropathy, we have chosen to focus our investigation on SIRT3." (PMID 38572816, 2024).
postmenopausal osteoporosis (1 paper, 2026). Metabolic disorder associated with fractures of the femoral neck, vertebrae, and distal forearm. "Our findings suggest that the novel Estrogen/SIRT5/FDX1 axis may function as a key regulator of bone homeostasis, and identify SIRT5 as a potential therapeutic candidate for postmenopausal osteoporosis, likely through its capacity to reduce the cuproptosis-like features of mesenchymal stem cells." (PMID 42290657, 2026).
rheumatoid arthritis (1 paper, 2025). A chronic, systemic autoimmune disorder characterized by inflammation in the synovial membranes and articular surfaces. "In rheumatoid arthritis (RA), meal timing reshapes gut microbial oscillations, influencing diurnal activation of the SIRT5–NF-κB inflammatory axis through Parabacteroides distasonis β-glucosidase–mediated release of glycitein, thereby driving time-of-day differences in immune activation." (PMID 41262263, 2025).
serous adenocarcinoma (1 paper, 2019). An adenocarcinoma that is characterized by the presence of papillary patterns and cellular budding. "Similarly, in our study, a higher mRNA level of SIRT5 was found in OC, especially in serous adenocarcinoma, and it was related to poor PFS in OC." (PMID 31572453, 2019).
serous ovarian carcinomas (1 paper, 2019). "In contrast, the region encompassing the SIRT5 locus was amplified in 30% of high-grade serous ovarian carcinomas." (PMID 31572453, 2019). "An analysis of human high-grade serous ovarian carcinomas revealed that the region encompassing the SIRT5 locus was amplified in 30% of these tumors." (PMID 31572453, 2019).
tauopathy (1 paper, 2019). Neurodegenerative disorders involving deposition of abnormal tau protein isoforms (tau proteins) in neurons and glial cells in the brain. "To test the role of sirtuins in the hydralazine-mediated recovery of mitochondrial function in tauopathy cell models, we treated SIRT1 and SIRT5 knockdown AP cells with hydralazine." (PMID 31659167, 2019).
tubal cancers (1 paper, 2019). "SIRT3 and SIRT5 expression were found to be significantly decreased and increased in primary serous OCs/tubal cancers compared with that in normal counterparts, respectively." (PMID 31572453, 2019). "Moreover, SIRT5 was found to increase in primary serous OCs/tubal cancers compared with that in normal tissues, and high expression of it was associated with better OS by univariable analysis." (PMID 31572453, 2019).
tumor (99 papers, 2014 to 2026). "Meanwhile, SHMT2 K280 succinylation is regulated by SIRT5, and the post-translational modification is inversely linked with osteosarcoma cell proliferation and tumor growth via regulation of the mitochondrion-carbon metabolism pathway." (PMID 40865948, 2025). "SIRT5 plays a role in suppressing tumour cell proliferation and is linked to a positive prognosis in individuals diagnosed with PDAC." (PMID 39778006, 2025). "For instance, SIRT1 has been shown to promote cancer progression by deacetylating and activating oncogenic transcription factors, while SIRT5 has been implicated in tumor suppression by regulating mitochondrial metabolism." (PMID 40710366, 2025). "Among these, SIRT1, SIRT4, and SIRT5 are the most highly implicated regulators, exhibiting both tumor-suppressive and tumor-supportive functions, depending on the cellular and tumor context." (PMID 41425553, 2025). "Recent studies have shown that the expression of SIRT5 negatively impacts tumor cell proliferation in PDAC patients and is associated with a favorable prognosis." (PMID 38773972, 2024). "Clinical studies have demonstrated that high SIRT5 expression is associated with reduced tumor cell proliferation and improved patient prognosis in PDAC." (PMID 39682281, 2024). "SIRT5 has also been associated with metabolic regulation and changes in the tumor microenvironment in promoting hepatocarcinogenesis." (PMID 37705968, 2023). "In this study, the authors also described that downregulation of SIRT5 leads to abnormal bile acid metabolism and favours M2-like tumour-associated macrophages." (PMID 36601059, 2022). "Accordingly, SIRT5 loss leads to a reductionin ROS levels and the consequent proliferation of tumor cells." (PMID 35802779, 2022). "Further statistical analysis showed that higher SIRT5 was significantly associated with malignant tumor characteristics such as larger tumor size, lymph node metastasis, advanced TNM stage, and poor survival." (PMID 31456942, 2019). "The protein level of SIRT5 is associated with tumor size, lymph node invasion, AJCC staging, and overall survival of patients with CRC." (PMID 29416026, 2018). "We found that SIRT5 overexpression was associated positively with larger tumor size (P = 0.036), increased lymph node metastasis (P = 0.016), advanced tumor stage (P = 0.038), and American Joint Committee on Cancer (AJCC) stage (P = 0.005)." (PMID 29416026, 2018). "This regulation is critical because altered metabolism is a hallmark of cancer, and SIRT5’s role in this process may contribute to its tumor-suppressive effects." (PMID 40710366, 2025). "SIRT5 deficiency results in high degree of succinylation, which increases the production of bile acid, promotes M2-like macrophage polarization, and creates an immunosuppressive tumor microenvironment favorable to tumor-initiating cells." (PMID 39979670, 2025). "Specifically, SIRT1, SIRT2, SIRT6, and SIRT7 are implicated in promoting PCa progression, while SIRT5 displays a paradoxical role, simultaneously aiding DNA repair and inhibiting apoptosis, yet fostering tumor growth through androgen receptor (AR) interactions." (PMID 39796040, 2024). "Additionally, loss of SIRT5 promotes the development of liver cancer by altering bile acid metabolism and fostering an immune-suppressive tumor environment." (PMID 38773972, 2024). "The inactivation of lactate dehydrogenase A (LDHA) because of desuccinylation on Lys118 is hypothesized to be the cause of the tumor suppressor function of SIRT5." (PMID 36980194, 2023).